MCRIP2 (MAPK regulated corepressor interacting protein 2)
Synonyms: C16orf14; FAM195A; MGC15416; c349E10.1
Tractability: No criterion of Open Targets' tractability assessment is met for any kind of drug.
Gene: Protein-coding gene on chromosome 16 (636,817 to 648,474, forward strand). Ensembl gene ENSG00000172366.
Subcellular location: Cytoplasm, Stress granule; Nucleus
Gene Ontology:
Molecular function: protein binding; protein-containing complex binding; RNA binding
Cellular component: cytoplasm; cytoplasmic stress granule; nucleus; cytosol
Genetic constraint (gnomAD): Loss-of-function variants: 19 observed, 15.54 expected, observed/expected ratio (o/e) 1.22, 90% interval 0.85 to 1.75. The synonymous counts are far from expectation, so gnomAD's model fits this gene poorly and the ratio says little. Missense variants: 233 observed, 166.1 expected, observed/expected ratio (o/e) 1.4, 90% interval 1.26 to 1.56. Synonymous variants: 121 observed, 79.98 expected, observed/expected ratio (o/e) 1.51, 90% interval 1.3 to 1.76.
Homologues: Orthologues: chimpanzee MCRIP2 (99% identical), pig MCRIP2 (89% identical), guinea pig MCRIP2 (87% identical), mouse Mcrip2 (85% identical), dog MCRIP2 (84% identical), rat Mcrip2 (78% identical), zebrafish mcrip2 (49% identical), tropical clawed frog mcrip2 (46% identical). Paralogues in human: FGFRL1 (31% identical), MCRIP1 (26% identical).
Diseases named in the same sentence as MCRIP2 in open-access papers:
MCRIP2 is named in the same sentence as 4 diseases in open-access papers, as found by Europe PMC text mining. Sharing a sentence is not in itself a finding about the gene and the disease. The quoted sentences say what the papers report.
pancreatic tumor (1 paper, 2023). "However, the role of COQ4, MCRIP2, MRPL50, MRPL14, RFK, and NMNAT3 in pancreatic tumor has not been reported." (PMID 37223030, 2023).
MCRIP2 also shares sentences with these, for which no sentence is quoted: Brachycephaly (1 paper); breast carcinoma (1); cholestasis (1).